GTF2H3 (general transcription factor IIH subunit 3)
Description:
Component of the general transcription and DNA repair factor IIH (TFIIH) core complex, which is involved in general and transcription-coupled nucleotide excision repair (NER) of damaged DNA and, when complexed to CAK, in RNA transcription by RNA polymerase II. In NER, TFIIH acts by opening DNA around the lesion to allow the excision of the damaged oligonucleotide and its replacement by a new DNA fragment. In transcription, TFIIH has an essential role in transcription initiation. When the pre-initiation complex (PIC) has been established, TFIIH is required for promoter opening and promoter escape. Phosphorylation of the C-terminal tail (CTD) of the largest subunit of RNA polymerase II by the kinase module CAK controls the initiation of transcription.
Synonyms: BTF2; TFIIH; P34; TFB4
Tractability: Small molecule: a structure with a bound ligand is known. PROTAC: ubiquitination databases record sites on it; its protein half-life has been measured.
Gene: Protein-coding gene on chromosome 12 (123,633,739 to 123,662,604, forward strand). Ensembl gene ENSG00000111358.
Subcellular location: Nucleus
Subcellular location (Human Protein Atlas): Nucleoplasm
Pathways (Reactome):
Gene expression (Transcription): Formation of RNA Pol II elongation complex; Formation of the Early Elongation Complex; NoRC negatively regulates rRNA expression; RNA Pol II CTD phosphorylation and interaction with CE; RNA Polymerase I Promoter Escape; RNA Polymerase I Transcription Initiation; RNA Polymerase I Transcription Termination; RNA Polymerase II Pre-transcription Events; RNA Polymerase II Promoter Escape; RNA Polymerase II Transcription Elongation; RNA Polymerase II Transcription Initiation; RNA Polymerase II Transcription Initiation And Promoter Clearance; RNA Polymerase II Transcription Pre-Initiation And Promoter Opening
Disease: Formation of HIV elongation complex in the absence of HIV Tat; Formation of HIV-1 elongation complex containing HIV-1 Tat; Formation of the HIV-1 Early Elongation Complex; HIV Transcription Initiation; RNA Pol II CTD phosphorylation and interaction with CE during HIV infection; RNA Polymerase II HIV Promoter Escape; Tat-mediated elongation of the HIV-1 transcript; Transcription of the HIV genome
DNA Repair: Dual Incision in GG-NER; Dual incision in TC-NER; Formation of Incision Complex in GG-NER; Formation of TC-NER Pre-Incision Complex; Gap-filling DNA repair synthesis and ligation in TC-NER; Transcription-Coupled Nucleotide Excision Repair (TC-NER)
Metabolism of RNA: mRNA Capping
Gene Ontology:
Molecular function: protein binding; RNA polymerase II general transcription initiation factor activity
Biological process: transcription by RNA polymerase II; DNA repair; nucleotide-excision repair; transcription initiation at RNA polymerase II promoter; regulation of DNA-templated transcription
Cellular component: core TFIIH complex portion of holo TFIIH complex; nucleoplasm; nucleus; transcription factor TFIID complex; transcription factor TFIIH holo complex; transcription preinitiation complex; transcription factor TFIIH core complex
Genetic constraint (gnomAD): Loss-of-function variants: 16 observed, 18.68 expected, observed/expected ratio (o/e) 0.86, 90% interval 0.58 to 1.3. The upper end of that interval is the gene's LOEUF score, 1.3, which puts it in group 5 of 6, group 1 being the genes least tolerant of losing a copy. Missense variants: 120 observed, 146.65 expected, observed/expected ratio (o/e) 0.82, 90% interval 0.7 to 0.95. Synonymous variants: 54 observed, 50.43 expected, observed/expected ratio (o/e) 1.07, 90% interval 0.86 to 1.34.
Homologues: Orthologues: macaque GTF2H3 (99% identical), chimpanzee GTF2H3 (99% identical), dog GTF2H3 (97% identical), pig GTF2H3 (97% identical), rabbit GTF2H3 (97% identical), guinea pig GTF2H3 (96% identical), mouse Gtf2h3 (94% identical), rat Gtf2h3 (93% identical), tropical clawed frog gtf2h3 (78% identical), zebrafish gtf2h3 (68% identical), Drosophila melanogaster Tfb4 (44% identical), Caenorhabditis elegans gtf-2H3 (25% identical).
Diseases named in the same sentence as GTF2H3 in open-access papers:
GTF2H3 is named in the same sentence as 9 diseases in open-access papers, as found by Europe PMC text mining. Sharing a sentence is not in itself a finding about the gene and the disease. The quoted sentences say what the papers report.
Immunodeficiency (1 paper, 2022). Failure of the immune system to protect the body adequately from infection, due to the absence or insufficiency of some component process or substance. "Such a pathological process induced by abnormal GTF2H3 expression may aggravate the immunodeficiency for individuals with Yang deficiency." (PMID 35341155, 2022).
Infertility (1 paper, 2024). "Whole-exome sequencing identified a single nucleotide variant (c.664T>C) in the GTF2H3 gene, which appears to be the probable cause of infertility in a Turkish family." (PMID 39596622, 2024).
yang deficiency (1 paper, 2022). Yang deficiency is a concept from traditional Chinese medicine. "In particular, KAT2B, NFKB2, CREBBP, and GTF2H3 were the key contributive targets for the Yang deficiency group." (PMID 35341155, 2022). "KAT2B, NFKB2, CREBBP, and GTF2H3 are represented as candidate markers for Yang deficiency." (PMID 35341155, 2022). "The symptomatic gene targets for Yang deficiency (KAT2B, NFKB2, CREBBP, GTF2H3) or Yin deficiency (JUNB, JUND, NGLY1, TNF, RAF1, PPP1R15A) were potentially discovered." (PMID 35341155, 2022).
GTF2H3 also shares sentences with these, for which no sentence is quoted: cancer (2 papers); viral infection (2); cervical carcinoma (1); Fanconi anemia (1); lung carcinoma (1); lung squamous cell carcinoma (1).